TCEANC (transcription elongation factor A N-terminal and central domain containing)
Synonyms: MGC17403; TCEANC1
Tractability: No criterion of Open Targets' tractability assessment is met for any kind of drug.
Gene: Protein-coding gene on chromosome X (13,653,078 to 13,681,964, forward strand). Ensembl gene ENSG00000176896.
Subcellular location (Human Protein Atlas): Nuclear speckles
Gene Ontology:
Molecular function: protein binding; transcription elongation factor activity
Biological process: transcription elongation by RNA polymerase II; DNA-templated transcription
Homologues: Orthologues: chimpanzee TCEANC (99% identical), macaque TCEANC (96% identical), guinea pig TCEANC (78% identical), pig TCEANC (70% identical), rat Tceanc (70% identical), mouse Tceanc (69% identical), tropical clawed frog tceanc (45% identical). Paralogues in human: TCEA3 (29% identical), TCEA2 (29% identical), TCEA1 (28% identical).
Diseases named in the same sentence as TCEANC in open-access papers:
TCEANC is named in the same sentence as 2 diseases in open-access papers, as found by Europe PMC text mining. Sharing a sentence is not in itself a finding about the gene and the disease. The quoted sentences say what the papers report.
Hypertension (1 paper, 2016). The presence of chronic increased pressure in the systemic arterial system. "Four single nucleotide polymorphisms (SNPs) at three new genes (L3MBTL4 rs403814, Pmeta = 6.128 × 10−9; LOC729251, and TCEANC) and seven SNPs at five previously reported genes were identified as being significantly associated with hypertension." (PMID 27480026, 2016). "The three other loci (rs4243170 of LOC729251 gene, rs2361159 and rs5935649 of TCEANC gene) nominally associated with hypertension (5 × 10−4 < Pmeta < 0.05)." (PMID 27480026, 2016). "In addition, we identified three SNPs in two novel genes (LOC729251 and TCEANC) and seven SNPs in five previously reported genes (FGF5, ATP2B1, CYP17A1, MTHFR and CASZ1) nominally associated with hypertension (Pmeta < 0.05)." (PMID 27480026, 2016).
cancer (1 paper, 2021). A tumor composed of atypical neoplastic, often pleomorphic cells that invade other tissues. "Many of the genes in this category are known oncogenes or tumor suppressors (e.g., DDX3X, TRAPPC2, and TCEANC), they play crucial roles in women’s cancer." (PMID 34725332, 2021).